IL6 (interleukin 6)
Diseases named in the same sentence as IL6 in open-access papers (continued):
Sharing a sentence is not in itself a finding about the gene and the disease.
cervical carcinoma (continued). "By electronic and manual searches concerning the association of IL-12B rs3212227 and IL-6 rs1800795 polymorphisms and cervical cancer risk, 297 relevant studies up to November 05, 2019 were identified." (PMID 32458622, 2020). "In cervical cancer, IL‐6 is reported to be highly upregulated and strongly associated with a poor outcome." (PMID 32491253, 2020). "Our pooled data revealed that IL-6 rs1800795 polymorphism was associated with an increased risk of cervical cancer in the overall population." (PMID 32458622, 2020). "The autocrine and paracrine actions of IL-6 are essential for STAT3 activation in HPV positive cervical cancers and loss of the pathway results in increased cancer cell death and a reduction in proliferation." (PMID 31226168, 2019). "Considering the link between inflammatory cytokine production and cervical cancer, various cytokines have been implicated in the pathogenesis of cervical cancer, among which IL-6 has received particular attention." (PMID 31470515, 2019). "Overall, our analysis indicates that the genotypes of IL-6 -174G>C polymorphism are associated with cervical cancer risk." (PMID 30135142, 2018). "Their results suggested that women carrying at least one C genotype in their IL-6 promoter region (-174G>C) are at higher risk of developing cervical cancer." (PMID 30135142, 2018). "Statistically significant relationship was observed between IL-6 -174G>C polymorphism and cervical cancer risk (OR = 0.61, 95% CI: 0.40–0.94 for GG vs. CC, and OR = 0.77, 95% CI: 0.64–0.93 for G vs. C)." (PMID 30135142, 2018). "Statistically significant relationship was observed between IL-6 -174G>C polymorphism and cervical cancer risk in the two genetic models (OR = 0.61, 95% CI: 0.40–0.94 for GG vs. CC, OR = 0.77, and 95% CI: 0.64–0.93 for G vs. C)." (PMID 30135142, 2018). "Interleukin-6 (IL-6) a proinflammatory cytokine known to be associated with cervical cancer and acts as an angiogenic promoter." (PMID 30558287, 2018). "Several case–control studies have been conducted to assess the association of IL-6 -174G>C (rs1800795) polymorphism with the risk of cervical cancer, yet with conflicting conclusions." (PMID 30135142, 2018). "To date, this meta-analysis represents the most powerful investigation in elucidating the role of IL-6 -174G>C in cervical cancer risk." (PMID 30135142, 2018). "This meta-analysis showed the evidence that the IL-6 -174G>C polymorphism was a low-penetrance susceptibility variant for cervical cancer." (PMID 30135142, 2018). "Their results showed that the C genotype of interleukin 6 rs1800795 is associated with higher cervical cancer risk." (PMID 30135142, 2018). "This meta-analysis explored the association between a commonly studied IL-6 -174G>C polymorphism and cervical cancer risk." (PMID 30135142, 2018). "Thorough analysis demonstrated that cervical cancer-derived IL-6 drives C/EBPβ-mediated CCL20 induction in cancer-associated fibroblasts and CCL20/CCR6-dependent Th17 recruitment." (PMID 28895886, 2017). "IL-6 up-regulation has been implicated as a significant element in cervical cancer pathogenesis by a number of studies." (PMID 26010154, 2015). "The pro-inflammatory cytokines IL-6 and IL-23, which are implicated in the induction of IL-17 expression, have also been shown to be correlated with poor survival in cervical cancer." (PMID 25795131, 2015). "With activated STAT3, IL-6 emerges senescent at early passages in cervical cancer tissues infected with high-risk HPV and activates the STAT3 and cellular senescence." (PMID 26308848, 2015). "Further, accumulating researches reported that polymorphisms of a series of genes, including interleukin (IL)-1, IL-6, and IL-12, were associated with the susceptibility to cervical cancer." (PMID 23049595, 2012). "In cervical cancer patients, high serum levels of IL-6 have been associated with adverse prognoses." (PMID 36769377, 2023).
cervical carcinoma (continued). "Furthermore, circulating IL-6 was found to be a risk indicator since elevated serum IL-6 levels correlate with advanced stages of cervical cancer." (PMID 36405719, 2022). "Allele G of IL-6 rs1800795 was associated with lower risk by 5.3-fold (95% CI 0.07–0.48), and genotype GG was associated with lower risk by 2.3-fold (95% CI 0.23–0.84) of cervical cancer." (PMID 34684062, 2021). "Allele C of IL-6 rs1800795 was associated with higher risk by 2.26-fold (95% CI 1.19–4.29), and genotype CC was associated with higher risk by 5.37-fold (95% CI 2.08–13.84) of cervical cancer." (PMID 34684062, 2021). "Our study’s aim was to evaluate the distribution of genotypes and allele frequencies of polymorphisms IL-6 597A/G (rs1800797) and 174G/C (rs1800795) among healthy women and cervical cancer patients, looking for a link between gene polymorphism and cervical cancer in the Lithuanian population." (PMID 34684062, 2021). "Duan and colleague’s results indicate that the C genotype of IL-6-174G>C polymorphism might be associated with higher cervical cancer risk as well." (PMID 34684062, 2021). "The current study showed that the IL-6 -572G>C polymorphism with risk of cervical cancer." (PMID 34582655, 2021). "The frequencies of C allele of IL-6 rs1800795 were significantly higher in cervical cancer cases, and logistic regression analysis indicated that cervical cancer risks were significantly higher in C allele carriers than those with GG genotype (GC+CC versus GG) in Chinese women." (PMID 34684062, 2021). "Other studies confirmed that allele G and genotype GG of IL-6 rs1800795 might have a protective effect against cervical cancer development." (PMID 34684062, 2021). "Our pooled data revealed that the IL-12B rs3212227 and IL-6 rs1800795 polymorphisms may be used to identify individuals at high risk of cervical cancer in Asian women." (PMID 32458622, 2020). "Thus, we systematically reviewed previous publications and a meta-analysis was conducted to evaluate the associations of IL-12B rs3212227 and IL-6 rs1800795 polymorphisms with risk of cervical cancer." (PMID 32458622, 2020). "In the recent years, several number of genome-wide association studies (GWAS) have been performed to evaluate the effects of different cytokines in development of cervical cancer, and many case-control studies have reported the association of IL-12 and IL-6 with an increased risk of cervical cancer." (PMID 32458622, 2020). "In summary, our pooled data revealed that IL-12B rs3212227 and IL-6 rs1800795 polymorphisms could be used to identify individuals at high risk of cervical cancer in Asian women." (PMID 32458622, 2020). "In conclusion, our results indicate that the C genotype of IL-6 -174G>C polymorphism might be associated with higher cervical cancer risk." (PMID 30135142, 2018). "Several studies have investigated the role of IL-6 -174G>C polymorphism in cervical cancer risk." (PMID 30135142, 2018). "The obtained results suggested IL-6 -174G>C polymorphism may influence cervical cancer risk in a low impact effect manner." (PMID 30135142, 2018). "The next protein in the high degree regime was IL6, whose variation in host immune response by single nucleotide polymorphisms may contribute in cervical cancer risk." (PMID 26308848, 2015). "Increased IL-17 expression is associated with cervical cancer cell growth along with IL-6 levels in tumor tissues; IL-17 may act through IL-6." (PMID 25810759, 2015). "However, a previous report has shown a significant association between the IL6-rs2069837 SNP and an increased risk of cervical cancer." (PMID 23936772, 2013). "Moreover, considering that ovarian and cervical cancers are multifactorial diseases which are characterized by a disruption of the cytokines, we hypothesized that IL-6 -174G>C and -572 G>C polymorphisms might be associated with the risk these cancers." (PMID 34582655, 2021).
cervical carcinoma (continued). "A meta-analysis by Liu and colleagues, including 1210 cervical cancer cases and 1525 controls from 5 studies from Brazil, China, India, Austria, and Finland, demonstrated that rs1800795 polymorphisms of IL-6 gene (G vs. C alleles) might be associated with susceptibility to cervical cancer." (PMID 34684062, 2021). "Moreover, the IL-6 -174G>C CC genotype (OR= 3.162, 95% CI: 1.094-9.141, p=0.034) and C allele (OR = 1.724; 95%CI: 1.129-2.633, p=0.012) was associated with increased risk of cervical cancer." (PMID 34582655, 2021). "Additionally, due to chronic inflammation, IL6 cytokine may increase the risk of developing cervical cancer." (PMID 26308848, 2015). "One of the primary mechanisms of cytokine storm in cervical cancer is the excessive release of cytokines such as IL-6, TNF-α, IL-1β, and IL-8." (PMID 41497141, 2026). "In the TME, cytokines such as IL-6 and IL-8 have been found to enhance several processes that are central to cervical cancer progression, such as angiogenesis, EMT, and cell migration." (PMID 41497141, 2026). "IL-6, in particular, is one of the most studied cytokines in cervical cancer, where it promotes the growth and survival of tumor cells." (PMID 41497141, 2026). "Particularly, IL-6 (with isoelectric points around 5.0), a representative cytokine, has the capacity to indicate the progression and clinical characteristics of cervical carcinoma." (PMID 40136934, 2025). "We found a significant increase in serum IL-6 levels of 214.9 ng/mL (95% CI: 60.1–369.7, p = 0.007) among women with cervical cancer (CC) compared to their cancer-free counterparts." (PMID 41561529, 2025). "IL-6 is a cytokine that can enhance the development and progression of various cancers, including cervical cancer." (PMID 39207449, 2024). "Breast, ovarian, and cervical cancer, as many other cancers, present elevated IL-6/JAK/STAT3 pathway activity." (PMID 38892394, 2024). "The current investigation elucidated that CEBPD serves as an upstream regulatory factor for key genes, including MYC, IL6, JUN, RRM2, and VEGFA, all of which have been linked to an unfavorable prognosis in cervical cancer patients." (PMID 38926832, 2024). "It has been documented that IL-6 signaling plays a critical role in a variety of cancers, as demonstrated by the elevated expression levels of IL-6 mRNA and protein in colorectal, prostate, breast, ovarian, pancreatic, and cervical cancer." (PMID 38275876, 2024). "STAT3 together with IL-6 can also lead to activation of epithelial to mesenchymal transition in BC and cervical carcinoma." (PMID 38892394, 2024). "The STAT3 signaling pathway induces the VEGF by stimulating IL-6 in C22A cervical carcinoma cell lines." (PMID 36865747, 2023). "APOBEC3A and pro-inflammatory factors IL-6 and NF-κB were more highly expressed in cervical cancer tissues than in adjacent normal tissues." (PMID 38021159, 2023). "Among the mechanisms involved, there was evidence that E6 and E7 proteins from HPV downregulates CCR7 by upregulating IL-6 in cervical cancer cell lines." (PMID 36831674, 2023). "At diagnosis, our findings showed that plasma levels of sHLA-G and IL-5, IL-6, IL-8, IL-10, IL-17, and were significantly increased in patients with cervical cancer." (PMID 36053326, 2023). "In particular, IL-6 promotes the survival of cervical cancer cells by upregulating the anti-apoptotic protein Mcl-1 via activation of the PI3K/Akt pathway." (PMID 36310590, 2022). "In this study, we observed that IL-6 knockdown significantly decreased the growth of cervical cancer cells." (PMID 36310590, 2022). "In women with cervical cancer, high levels of IL-6 expression in the cancer microenvironment promote angiogenesis and the development of cancer." (PMID 36010256, 2022).
cervical carcinoma (continued). "To further determine the function of IL-6 in cervical cancer progression, we analyzed the IL-6 protein expression in cervical cancer tissues by immunohistochemistry, and found that the in situ expression of IL-6 was significantly higher in the tumor tissues." (PMID 36310590, 2022). "Consistent with this, previous studies have reported the involvement of various cytokines in Orai1-regualted cervical cancer cell growth, especially that of IL-6." (PMID 36310590, 2022). "We found that Orai1 was upregulated in human cervical cancer tissues, and silencing Orai1 suppressed the growth of cervical cancer cells in vitro and in vivo via inhibition of IL-6 secretion." (PMID 36310590, 2022). "IL-6 plays a crucial role in the proliferation and differentiation of malignant cells and it is known to be implicated in the pathogenesis of HPV+ cervical cancer." (PMID 36405719, 2022). "IL-6 has been reported to be upregulated in patients with many types of cancers, including cervical cancer, and is considered to play an important role during tumorigenesis." (PMID 36010256, 2022). "Gene silencing of Orai1 in cervical cancer cells significantly decreased interleukin (IL)-6 secretion." (PMID 36310590, 2022). "In this study, we found that Orai1 is upregulated in cervical cancer tissues compared to normal cervical tissues, and its high expression levels correlated positively with that of IL-6." (PMID 36310590, 2022). "Consistent with this, pre-treatment with IL-6 enhanced the clonogenicity of Orai1-knockdown cervical cancer cells, indicating that IL-6 lies downstream of Orai1." (PMID 36310590, 2022). "To further validate role of IL-6 in Orai1-mediated cell growth, we treated the Orai1-silenced cervical cancer cells with recombinant IL-6." (PMID 36310590, 2022). "In cervical cancer, cases that produce G-CSF are very rare, while the production of IL-6 from different cell lines of uterine cervical cancers and cases of IL-6-producing cervical cancer have been reported." (PMID 36010260, 2022). "Compared to the normal cervix and cervical intraepithelial neoplasia (CIN), the expression of IL-6 in cervical cancer was considerably higher." (PMID 36405719, 2022). "The tested IL-6 six SNPs’ genotype distribution, including IL-6 rs1800797 and IL-6rs1800795, was similar between both cervical cancer cases and control groups." (PMID 34684062, 2021). "The upregulation of lncRNA-UICC and IL6 signaling in cervical cancer promotes tumorigenesis and metastasis in cervical cancer." (PMID 35126382, 2021). "IL-6 in cervical cancer is a known potential biomarker that acts by inducing vascular epithelial growth factor-dependent angiogenesis in a STAT3-dependent manner and promoting tumor proliferation." (PMID 34445405, 2021). "The IL-6 also has a similar mechanism to IL-8 in the pathophysiology of cervical cancer, with the difference that the IL-6 tumorigenic activity is often applied by stimulating proliferation and reducing apoptosis." (PMID 33906316, 2021). "We mainly focused on IL-6, which has been demonstrated to be one of the key players for the development and progression of cervical cancer cells with HPV infection." (PMID 34371622, 2021). "In this meta-analysis, we explore the role of XRCC3 rs861539, MTHFR rs1801133, IL-6 rs1800795, IL-12B rs3212227, TNF-α rs1800629, and TLR9 rs352140 polymorphisms in susceptibility to cervical cancer." (PMID 34837895, 2021). "In this meta-analysis, the association of XRCC3 rs861539, MTHFR rs1801133, IL-6 rs1800795, IL-12B rs3212227, TNF-α rs1800629 and TLR9 rs352140 polymorphisms with susceptibility to cervical carcinoma was assessed by including all relevant studies." (PMID 34837895, 2021). "Our study aimed to evaluate the distribution of genotypes and allele frequencies of IL-6 597A/G (rs1800797) and 174G/C (rs1800795) polymorphisms in HPV infected and uninfected healthy women and cervical cancer patients." (PMID 34684062, 2021).
cervical carcinoma (continued). "In our previous study, we have found increased serum levels of inflammatory markers—TNF-α, IFN-β, IL-1β, sTREM-1, IL-6—in cervical cancer patients." (PMID 34684062, 2021). "Meanwhile, the inflammatory cytokines, such as IL-6, IL-8, and IL-1β can promote tumor proliferation and the occurrence and development of cervical cancer." (PMID 33849528, 2021). "We performed this meta-analysis to explore the role of XRCC3 rs861539, MTHFR rs1801133, IL-6 rs1800795, IL-12B rs3212227, TNF-α rs1800629 and TLR9 rs352140 polymorphism with susceptibility to cervical carcinoma." (PMID 34837895, 2021). "Experiments have shown that cervical cancer cells secreted prostaglandin (PG) E2 and IL-6 to induce M2 phenotype and produce CCL2 to promote the recruitment of monocytes at the tumor site." (PMID 34717710, 2021). "Inhibition of IL‐6 expression in cervical cancer cells by siRNA transfection almost completely reversed the effects of poly(I:C) treatment." (PMID 31943744, 2020). "The IL-6 expressed in HPV positive cervical cancer cells then facilitates autocrine STAT3 activation via JAK/IL-6R." (PMID 32915198, 2020). "These two observations suggested that the involvement of poly(I:C) promoted IL‐6 secretion of cervical cancer in the regulation of cellular behaviours of macrophages." (PMID 31943744, 2020). "In other hand, exosomal miR‐223 derived from cervical cancer cells induces IL‐6 secretion from monocyte/macrophage, which, in turn, activates STAT3 signals in cervical cancer cells." (PMID 32491253, 2020). "The enhanced IL‐6 expression in cervical cancer cells through the NF‐κB signalling pathway was shown as a critical factor in the modulation of poly(I:C)‐stimulated cervical cancer cells on macrophages." (PMID 31943744, 2020). "poly(I:C)‐stimulated supernatant of cervical cancer cells promoted M1‐type cytokine IL‐1β and IL‐6 expression of THP‐1–derived macrophages, but inhibited the expression of M2‐type cytokine, IL‐10 and CCL22." (PMID 31943744, 2020). "When cervical cancer cells were treated with IL‐6 which is a major stimulator of STAT3 signaling, the miR‐223 level significantly increased in a dose‐dependent manner." (PMID 32491253, 2020). "The promotion of IL‐1β and IL‐6 expression of macrophages by poly(I:C)‐treated supernatants was reversed by IL‐6 siRNA interfering in cervical cancer cells." (PMID 31943744, 2020). "In this study, we explored the role of poly(I:C) in HPV‐positive cervical cancer cells and found that poly(I:C) promotes the expression of IL‐6 in cervical cancer cells by activating the NF‐κB signalling pathway." (PMID 31943744, 2020). "EGFR ligands such as amphiregulin and TGFα were upregulated by IL-6 via an EGFR-dependent pathway of autocrine stimulation in human cervical carcinoma cells and virus-immortalized cells." (PMID 32709896, 2020). "The up‐regulation of IL‐6 secretion was found after 2 hours of poly(I:C) treatment in both two cervical cancer cell lines." (PMID 31943744, 2020). "For example, through NFκB activity, cervical cancer cells secrete IL-6, which in turn activates STAT3 with a pro-tumoral effect." (PMID 33330068, 2020). "We further explored the role of IL‐6 in the promotion of macrophage recruitment by cervical cancer cells in poly(I:C)." (PMID 31943744, 2020). "In conclusion, we found that poly(I:C) promoted the secretion of IL‐6 by cervical cancer cells through activation of the NF‐κB pathway." (PMID 31943744, 2020). "The results showed that the addition of cervical cancer cell supernatant during the differentiation of monocytes into macrophages inhibited the expression of M1 cytokines such as IL‐1β and IL‐6 and promoted M2 cytokines such as IL‐10 and CCL22 expression." (PMID 31943744, 2020). "Results showed that the expression profiles of cytokines detected in the two cervical cancer cell lines were consistent and IL‐2, IL‐4, IL‐6, IL‐8, IFN‐γ, MCP‐1 and TNF‐α were all expressed." (PMID 31943744, 2020).